MAP3K1 (mitogen-activated protein kinase kinase kinase 1)
Diseases named in the same sentence as MAP3K1 in open-access papers (continued):
Sharing a sentence is not in itself a finding about the gene and the disease.
breast cancer (continued). "In two patients, we found two mutations (MAP3K1 L380fs and PIK3CA I391M, respectively) present in the mastopathy as well as in the subsequent breast cancer." (PMID 31396514, 2019). "In line with this, we observed enhanced levels of WNT7B in breast cancer cells with loss-of-function mutations in MAP2K4 and MAP3K1." (PMID 31766464, 2019). "Loss-of-function mutations in the JNK signaling pathway (e.g. MAP3K1, MAP2K4, and MAP2K7) are implicated in the etiology of breast cancer." (PMID 29856313, 2018). "MAP3K1 acts upstream of MAP2K4 in signaling and in the METABRIC breast cancer study, loss-of-function mutations in these genes is mutually exclusive (p < 0.001)." (PMID 29795445, 2018). "For example, loss‐of‐function mutations in MAP3K1 and MAP2K4, two kinases involved in activation of JNK, are most commonly found in luminal breast cancer of which approximately 15% contain mutations in either gene." (PMID 30190333, 2018). "In the TCGA data on breast cancers, MAP3K1 alterations were more frequently found in the luminal A subtype than in other subtypes of breast cancers." (PMID 28178648, 2017). "Functional analysis and validation of the biologic significances of SNPs of CYP2B6 rs3211371 and MAP3K1 rs889312 in this subtype of breast cancer patients are warranted." (PMID 28178648, 2017). "In Latinas, 4 (MAP3K1, ZMIZ1, FGFR2, and TOX3) of the 12 regions have been associated with breast cancer in 1497 cases and 3213 controls." (PMID 27814745, 2016). "To further delineate the involvement of artificial miRNA-induced MAP3K1 depletion in breast cancer progression, we investigated the in vivo growth and metastasis of breast cancer cells using nude mice model." (PMID 26759750, 2016). "HE staining analysis also revealed that overexpression of Map3k1 amiRNA-3 reduced the rate of lung metastasis and invasive behavior of breast cancer cells in nude mice xenograft model." (PMID 26759750, 2016). "Of great importance, we showed that miRNA-based MAP3K1 targeting significantly suppressed the proliferation and invasion of breast cancer cells." (PMID 26759750, 2016). "Taken together, these data indicated that Map3k1 amiRNA-induced MAP3K1 depletion inhibited the growth and lung metastasis of breast cancer cells." (PMID 26759750, 2016). "The rate of EDU incorporation declined remarkably after Map3k1 amiRNA transduction, suggesting that Map3k1 amiRNA significantly impaired the proliferation of 4T1 breast cancer cells." (PMID 26759750, 2016). "These genes include TP63 for bladder cancer, FGFR2 and MAP3K1 for breast cancer, HNF1B for ovarian cancer, KLK3 for prostate cancer, and CDKN2A for skin cancer." (PMID 26374197, 2015).
breast cancer (continued). "From its initial discovery as the second Map2k1 kinase to defining the role of Map3k1 signal transduction in tumorigenesis and breast cancer, the road to understanding the intricate mechanisms of Map3k1 signaling has seemed to go on forever." (PMID 25613373, 2015). "The associations between mitogen-activated protein kinase kinase kinase 1 (MAP3K1) SNPs rs889312 A>C, rs16886165 T>G and breast cancer risk have been widely evaluated, but the results were inconsistent." (PMID 24595411, 2014). "Out of the top ten mutated genes in the large breast cancer investigation of The Cancer Genome Atlas (TCGA), we found mutations in seven of these (PIK3CA, GATA3, MAP3K1, MLL3, CDH1, PTEN, TBX3)." (PMID 24998755, 2014). "Four further genes, FGFR2, LSP1, MAP3K1, and TOX3, were associated with a mild increase in risk of breast cancer in a GWAS; however over 50% of breast cancers occur in women who do not carry these higher risk genotypes." (PMID 23738139, 2013). "For the 12p11 (PTHLH), 5q11 (MAP3K1), and 9p21 (CDKN2A/B), we found uncorrelated SNPs that had stronger associations than the originally identified SNP in the breast cancer susceptibility region that should be replicated in the general population." (PMID 23544012, 2013). "Recent genome-wide association studies revealed strong evidence for more than 18 common breast cancer susceptibility alleles including FGFR2, CCND1, TNRC9, MAP3K1, and LSP1." (PMID 23226154, 2012). "Studies from genomewide association studies (GWASs) in breast cancer reveal SNPs in five genes (TNRC9, FGFR2, MAP3K1, H19, and LSP1) are associated with breast cancer susceptibility in European population." (PMID 22778704, 2012). "Prominent examples are genome-wide association studies which led to the identification of novel breast cancer risk factors such as polymorphisms in FGFR2, CCND1, TOX3, MAP3K1, LSP1, CDKN2A, and 2B." (PMID 23226154, 2012). "Six of the previously identified SNPs showed a statistically significant association with breast cancer risk: rs2981582 (FGFR2), rs3803662 (TNRC9), rs12443621 (TNRC9), rs889312 (MAP3K1), rs3817198 (LSP1) and rs2107425 (H19)." (PMID 22867275, 2012). "MAP3K1 and SLC4A7/NEK10 were associated only with risk of PR-positive breast cancer among BRCA2 mutation carriers." (PMID 22053997, 2011). "However, a tumor suppression role has also been postulated for MAP3K1, at least in the breast cancer model." (PMID 40965626, 2025). "Whether other genes play a role in the immune escape of HR+/HER2– breast cancer, and whether MAP3K1 can modulate the immunity in other cancer types remains unknown." (PMID 39531335, 2024). "Similarly to MAP3K1, α2 integrin down-regulation or pharmacological inhibition impaired breast cancer cell invasion in 3D systems." (PMID 39666682, 2024). "To further investigate the effect of MAP3K1 mutation on tumor progression, we knocked out its endogenous expression and then overexpressed either Map3k1 WT or C-terminus kinase domain-truncated mutant (mut) in murine luminal breast cancer cell lines 67NR and EMT6." (PMID 39531335, 2024).
breast cancer (continued). "In addition to numerous studies focused on somatic mutations in MAP3K1, GWAS revealed associations between SNPs, including rs7714232 and rs16886272 regulating the expression of MAP3K1, and breast cancer." (PMID 35176995, 2022). "In addition, rs2981582 in FGFR2, rs16886165 in MAP3K1 and rs3803662 in TOX3 are associated with breast cancer in populations of European ancestry, and the first two were also associated with breast cancer in Uruguay." (PMID 33126731, 2020). "MAP3K1 was a key isoform for the first stimulation step of MAPKs and worked as an oncogene involved in the regulation of cell growth, migration, apoptosis and chemoresistance in multiple cancers such as gastric cancer, glioma, breast cancer." (PMID 33057597, 2020). "Thus, co-occurrence of MAP3K1 and PIK3CA mutations is associated with a strong luminal A-like phenotype in ER+ breast cancer." (PMID 31552290, 2019). "In one case, a MAP3K1 L380fs mutation was present in the mastopathy as well as in the tumor tissue, and in another case, a PIK3CA I391M mutation was present in the mastopathy as well as in the subsequent breast cancer." (PMID 31396514, 2019). "Finally, analysis of 166 estrogen receptor (ER) positive human breast cancer cases showed enhanced levels of WNT7B in breast cancers with loss-of-function mutations in the upstream JNK pathway components MAP2K4 and MAP3K1." (PMID 31766464, 2019). "For the UBC-TAM Series univariate analysis, favorable prognostic associations for breast-cancer-specific survival (BCSS) were detected for non-silent mutations in MAP3K1, ERBB3, XBP1, and PIK3CA." (PMID 30181556, 2018). "Considering the fact that PIK3CA and MAP3K1 were ranked as the most recurrently mutated genes, PI3K signalling pathway and MAPKKK cascade pathway were supposed to be essential pathways during the oncogenesis of breast cancer." (PMID 29485617, 2018). "In the present study, we demonstrated that genetic variants of the host, such as SNPs of MAP3K1, CYP2B6, UGT1A1, HCN1, ABCB1, and ALDH3A1, may worse the prognosis of HR-positive breast cancer patients, predominantly for premenopausal women." (PMID 28178648, 2017). "Additionally, using nude mice, we identified that Map3k1 amiRNA treatment attenuated the progression and lung metastasis of breast cancer in vivo." (PMID 26759750, 2016). "Moreover, we revealed that blockage of MEKK1 using artificial Map3k1 amiRNA suppressed the growth, lung metastasis and invasion of breast cancer." (PMID 26759750, 2016). "In addition, Map3k1 amiRNA induced marked proliferative impairment and invasive attenuation in breast cancer cells." (PMID 26759750, 2016). "Because ERK and p-38 signaling have been documented to regulate the growth and invasion of breast cancer cells, we analyzed whether transfection of Map3k1 amiRNA-3 could influence the growth of breast cancer cells." (PMID 26759750, 2016). "Using a miRNA-expressing lentivirus system, we delivered a artificial miRNA (Map3k1 amiRNA) that targets MAP3K1 into 4T1 breast cancer cells and investigated the impact of MAP3K1-targeting miRNA on the growth and invasive behavior of breast cancer in vitro and in vivo." (PMID 26759750, 2016). "Taken together, our findings explicitly indicated that MEKK1 exerted important oncogenic property in breast cancer development, and MAP3K1-targeting artificial miRNA may provide promising therapeutic effects in the treatment of breast cancer." (PMID 26759750, 2016).
breast cancer (continued). "Taken these information into account, we speculated that Map3k1 amiRNA may decrease the growth and metastasis of breast cancer cells through the regulation of multiple signaling pathways." (PMID 26759750, 2016). "Moreover, using in vivo nude mice model, we identified that Map3k1 amiRNA attenuated tumor growth and lung metastasis of breast cancer cells." (PMID 26759750, 2016). "In the present study, we showed that synthetic MAP3K1-targeting artificial miRNA may provide considerable beneficial effects in the prevention of breast cancer growth and metastasis." (PMID 26759750, 2016). "Because ERK and p-38 were reported to play regulatory roles in the invasion of breast cancer cells, we addressed whether overexpression of Map3k1 amiRNA-3 might inhibit the migration and invasion of breast cancer cells." (PMID 26759750, 2016). "To further elucidate the role of Map3k1 amiRNA in the regulation of breast cancer metastasis, we assessed whether Map3k1 amiRNA-3 could impair the ability of 4T1 cells to colonize the lungs of Balb/c nude mice." (PMID 26759750, 2016). "We replicated previously reported breast cancer susceptibility alleles in these BRCA2 mutation carriers and for several regions (including FGFR2, MAP3K1, CDKN2A/B, and PTHLH) identified SNPs that have stronger evidence of association than those previously published." (PMID 23544012, 2013). "Although this study suggested variation in four genes, MAP3K1, MMP9, TANK, and TLR9, may affect the risk of breast cancer, previous studies have observed associations for other genes in TLR or NFκB pathways." (PMID 23634849, 2013). "Previously reported BRCA2-modifying alleles for breast cancer, including those in FGFR2, TOX3, MAP3K1, LSP1, 2q35, SLC4A7, 5p12, 1p11.2, ZNF365, and 19p13.1 (ER-negative only), are also associated with breast cancer risk in the general population and/or BRCA1 mutation carriers." (PMID 23544012, 2013). "We found statistically significant evidence of association with breast cancer for eight of the 10 breast cancer susceptibility loci examined: FGFR2-rs2981582, TNRC9-rs3803662, 1p-rs11249433, 5p-rs7716600, 2q35-rs13387042, MAP3K1-rs889312, 8q24-rs13281615, and RAD51L1- rs999737." (PMID 22433456, 2012). "To examine whether regulators of ECM internalisation may impact on chemoresistance in breast cancer patients, we looked at the correlation between MAP3K1, MAPK11, PPP2R1A, and α2 integrin expression and chemotherapy response using transcriptomic data of 3,104 breast cancer patients." (PMID 39666682, 2024). "However, although several studies have focused on the association between MAP3K1 polymorphisms and hormone-related cancers such as breast cancer, no studies have confirmed the association between GC risk and this gene polymorphism by sex." (PMID 36510163, 2022). "MAP3K1 participates in the MAPK signal transduction pathway, responding to a number of mitogenic and metabolic stimuli, including estrogen, which may influence breast cancer susceptibility by cell proliferation." (PMID 28178648, 2017). "Thus, it remains unclear about the detailed role of p38 in breast cancer physiology following Map3k1 amiRNA overexpression." (PMID 26759750, 2016). "Also, it was demonstrated that MAP3K1 was related to human breast cancer progression, thus, MAP3K1 may play a vital role in keeping bovine mammary gland function well." (PMID 28030618, 2016).
breast cancer (continued). "A breast cancer association was seen for six of the 14 tested SNPs; rs2981582 (FGFR2) 1.28 (1.12-1.47), rs3803662 (TNRC9) 1.20 (1.04-1.39), rs12443621 (TNRC9) 1.19 (1.04-1.35), rs889312 (MAP3K1) 1.18 (1.02-1.36), rs3817198 (LSP1) 1.17 (1.10-1.35) and rs2107425 (H19) 0.86 (0.75-0.99)." (PMID 22867275, 2012). "Although allele frequencies of 5q11.2/MAP3K1 rs889312 (like 16q12.1/TOX3 rs3803662) were substantially different between Europeans and Koreans, the rs889312 C allele was also significantly associated with increased risk of breast cancer (OR = 1.16; 95% CI = 1.06 to 1.27; Ptrend = 8.49 × 10-4)." (PMID 22452962, 2012). "Further analysis has shown that allelic variation at FGFR2, TNRC9, 8q24, 2q35, and 5p12 is associated with physiological characteristics of breast tumors, such as ER status, and specific FGFR2, MAP3K1, and TNRC9 variants may interact with BRCA1 and BRCA2 mutations to increase breast cancer risk." (PMID 21037853, 2010). "Established markers for breast cancer cells (BRCA1, MAP3K1, BMPR1A) and fibroblasts (FN1, VIM, COL6A2) were used to classify the clusters." (PMID 39805002, 2025). "For breast cancer, there were 6 genes with a posterior probability > 0.9: BRCA2, BRCA1, PALB2, CHEK2, ATM, and MAP3K1." (PMID 40073867, 2025). "Consistently, we showed that MAP3K1, MAPK11, PPP2R1A, and α2 integrin expression is higher in chemoresistant breast cancer patients." (PMID 39666682, 2024). "A total of 18 cancer genes including ERBB2/HER2, ATR, ESR1 and MAP3K1 were identified to be LateN-to-EarlyT replicated in BRCA and affected by an APOBEC3-mediated omikli event in at least one tumour in the breast cancer cohort." (PMID 39019871, 2024). "Their data showed that RUNX1, PTEN, MAP3K1, and CDH1 had the highest impact in distinguishing survival curves of premenopausal and postmenopausal breast cancer." (PMID 38919805, 2024). "Strikingly, MAP3K1, MAPK11, PPP2R1A, and α2 integrin expression were higher in chemotherapy-resistant tumours in breast cancer patients." (PMID 39666682, 2024). "Consistent with our data showing a correlation between MAP3K1 levels and poor prognosis in PDAC patients, MAP3K1 expression correlates with progression and poor prognosis of hormone-receptor-positive, HER2-negative early-stage breast cancer patients." (PMID 39666682, 2024). "Potential therapeutic inbreast cancer by regulating breast cancer-related genes,including SERPINE1, PGAP3, MAP3K1, MAPK1, GSTO2, VIM, SPARC, and FGF2." (PMID 37191432, 2023). "MAP3K1 participates in the MAPK signaling pathway and can inhibit the proliferation of breast cancer cells, playing a vital role in maintaining good breast function." (PMID 36685859, 2022). "MDA-MB-468 breast cancer, H358 lung cancer and HCT116 colon cancer cells in which MAP3K1 or MAP2K4 was knocked out all show a marked increase in sensitivity to selumetinib." (PMID 29795445, 2018). "Moreover, our findings supported that synthetic artificial miRNA that targets MAP3K1 exert remarkable growth-inhibitory and anti-metastatic effects in breast cancer cells, highlighting that artificial miRNA may confer significant anti-tumor activity through modulating the expression of oncoproteins." (PMID 26759750, 2016).